APLN (apelin)
Diseases named in the same sentence as APLN in open-access papers (continued):
Sharing a sentence is not in itself a finding about the gene and the disease.
colorectal cancer (21 papers, 2014 to 2025). A primary or metastatic malignant neoplasm that affects the colon or rectum. "This highlights apelin-dm as a promising and safe therapeutic strategy for colorectal cancer and its associated metastatic liver events, paving the way for targeted clinical interventions." (PMID 39962271, 2025). "Indeed, Galectin-3-binding protein (LGALS3BP), gelsolin (Gsn), and Spartin (Spg20), which are associated with a favorable clinical outcome in colorectal carcinoma are downregulated in APLN-expressing cells and upregulated in APLN-DM-expressing cells." (PMID 39962271, 2025). "In colorectal cancer, apelin concentration becomes a predictive indicator, influencing responses to bevacizumab therapy and affecting susceptibility to apoptosis-inducing agents." (PMID 39962271, 2025). "In colorectal cancer, high APLN protein expression was correlated with poor progression-free survival in bevacizumab-treated patients." (PMID 36614283, 2023). "Group C intervention altered the endocrine system, Apelin and FoxO signaling pathways, colorectal cancer, microRNAs in cancer, endocrine and metabolic diseases, and platinum drug resistance." (PMID 37833670, 2023). "Similar findings were reported in colorectal cancer, where apelin and its receptor had higher expression in tumor tissue and serum samples of patients." (PMID 33707612, 2021). "In summary, our studies indicate that apelin and its receptor expression is upregulated in primary colorectal cancer." (PMID 31547096, 2019). "According to our knowledge, this is the first study focusing on mRNA and protein level of apelin and its receptor in primary colorectal carcinoma patients." (PMID 31547096, 2019). "In colorectal cancer, a high concentration of apelin predicted poor response to bevacizumab therapy." (PMID 29875677, 2018). "Apelin-derived peptides- [Pyr1]-apelin-13, apelin-13, and apelin 36, protected colorectal cancer cells from apoptosis induced by pro-apoptotic factors." (PMID 29875677, 2018). "In keeping with this, a recent study reports the high expression of apelin in colorectal cancer-isolated endothelial cells, which further correlates with refractoriness to anti-angiogenic treatment." (PMID 29053791, 2017). "Specifically, they detected apelin gene upregulation in 7 of 20 colorectal cancers using cancer-profiling arrays on cDNA samples from normal and tumor tissues of the same patient." (PMID 28422056, 2017). "LS180 proliferation was inhibited by blocking either APJ or Notch3, suggesting that apelin-13/APJ could promote colorectal cancer cell proliferation by modulating Notch3 pathways." (PMID 33912466, 2021). "Summarizing, all these results suggest that apelin could be an important factor in colorectal cancer progression and it has the potential to be a prognostic factor, however further research connected with clinical endpoints is necessary." (PMID 31547096, 2019). "In this study, we examined apelin and apelin receptor expression level in colorectal cancer." (PMID 31547096, 2019). "This is in line with recent data in 30 patients with colorectal cancer, suggesting that Apelin expression may represent a predictive biomarker for bevacizumab unresponsiveness, independently confirming our results in human patients." (PMID 31267692, 2019). "Apelin level was demonstrated to increase in colorectal carcinoma." (PMID 31547096, 2019). "On the basis of these literature data, we hypothesised that level of apelin, as peptide released by adipose tissue, could be altered in colorectal carcinoma patients and correlate with CRC development." (PMID 31547096, 2019). "Obtained results suggest that apelin could be an important factor in progression of colorectal carcinoma." (PMID 31547096, 2019). "Presented results suggest that apelin could be an important factor in the progression of colorectal carcinoma." (PMID 31547096, 2019).
colorectal cancer (continued). "We demonstrated recently a direct association of apelin expression with angiogenesis and clinical outcome in human non-small cell lung cancer and, moreover, showed that autocrine apelin/APJ signaling participates in human colorectal cancer growth." (PMID 24962866, 2014). "Thus, apelin may be used as a novel biomarker in predicting bevacizumab response in patients with colorectal cancer." (PMID 33912466, 2021). "Among breast and colorectal cancer survivors, randomization to 12 weeks of aerobic exercise increased LIF and IL‐15, whereas randomization to 12 weeks of metformin reduced apelin and IL‐15." (PMID 38887915, 2024). "The link between Apelin (APL)/APL receptor (APJ) and Jagged (JAG)/Notch signaling pathways in colorectal cancer (CRC) has been poorly investigated." (PMID 29254197, 2017). "According to our knowledge, there is no study including quantitative analysis of apelin and its receptor expression in colorectal carcinoma patients." (PMID 31547096, 2019).
endothelial dysfunction (21 papers, 2012 to 2026). In vascular diseases, endothelial dysfunction is a systemic pathological state of the endothelium (the inner lining of blood vessels) and can be broadly defined as an imbalance between vasodilating and vasoconstricting substances produced by (or acting on) the endothelium. "The disrupted balance between vasodilation and vasoconstriction in PCOS, driven by altered levels of NO, apelin, noradrenaline, and prostacyclin, contributes to endothelial dysfunction and increased cardiovascular risk." (PMID 40911578, 2025). "Here, we show that apelin associates independently with arterial stiffness and endothelial dysfunction, both surrogate measures of cardiovascular risk." (PMID 35748053, 2022). "Similarly, in HF patients, infusion of apelin locally caused vasodilatation despite evidence of endothelial dysfunction indicated by attenuated dilatation induced by acetylcholine." (PMID 26143239, 2015). "The observed increase of glomerular permeability with apelin may, therefore, be relevant during the early stages of DN, thereby supporting the concept that endothelial dysfunction is causally linked to DN." (PMID 23577111, 2013). "ERA is associated with alterations of serum ADMA and apelin levels, which might be used as biomarkers to detect early endothelial dysfunction in these patients." (PMID 22927708, 2012). "In cardiometabolic HFpEF, apelin expression is typically suppressed within epicardial and perivascular adipose tissue, paralleling systemic endothelial dysfunction." (PMID 41596265, 2026). "In this study, it is revealed that apelin relived diabetic cardiomyopathy via increasing angiogenesis and decreasing endothelial dysfunction, which were dependent on endothelial APJ activated NFκB pathway." (PMID 33504680, 2021). "Apelin is an adipokine that improves endothelial dysfunction; has anti-inflammatory and antioxidant effects; moreover, its level reduced during PE." (PMID 33850656, 2021). "The aims of the present study were to investigate the mechanism of MGO-induced endothelial dysfunction, and the cytoprotective role of apelin-13 in MGO-induced UPR and aortic endothelial dysfunction." (PMID 32517197, 2020). "Ferritinophagy-induced cell death has been implicated in cigarette smoke-induced chronic obstructive pulmonary disease (COPD), apelin-13-induced cardiomyocyte hypertrophy, sepsis-induced cardiac injury, and zinc oxide nanoparticle-induced endothelial dysfunction." (PMID 41515376, 2025). "However, in diabetic mice, exogenous apelin-13 administrations at a dose of 30 μg/kg/day exacerbated podocyte effacement, endothelial dysfunction, endoplasmic reticulum stress, and impaired autophagy in the kidneys." (PMID 40177358, 2025). "Given its role in vascular diseases, targeting apelin signaling could help modulate vascular inflammation and endothelial dysfunction in AS and IS." (PMID 40606664, 2025). "First, apigenin increases apelin expression to rescue endothelial dysfunction." (PMID 35495935, 2022). "MGO-induced endothelial dysfunction was significantly improved by apelin-13." (PMID 32517197, 2020). "Whether apelin-mediated vasoconstriction is physiologically relevant is debatable, but it may be of relevance in conditions of endothelial dysfunction." (PMID 26143239, 2015). "Moreover, Apelin improves endothelial dysfunction to alleviate acute liver and kidney injury in PE." (PMID 38718074, 2024). "Additionally, there was a positive correlation between apelin and arterial stiffness, measured by pulse wave velocity, and endothelial dysfunction, measured by flow‐mediated dilation, with arterial stiffness also significantly correlated with plasma ELA concentrations." (PMID 35748053, 2022).
endothelial dysfunction (continued). "The goal of the study is to investigate the molecular mechanism by which MGO induces endothelial dysfunction via the regulation of ER stress in endothelial cells, and to examine whether apelin-13, a cytoprotective polypeptide ligand, protects MGO-induced aortic endothelial dysfunction." (PMID 32517197, 2020). "Therefore, it was hypothesized that apelin might protect MGO-induced endothelial dysfunction via downregulating ER stress." (PMID 32517197, 2020). "In conclusion, the results of the present study indicate that apelin treatment in mice affects blood pressure in cases where blood pressure that is relatively low under normal conditions becomes elevated under the pathological conditions that are induced by endothelial dysfunction in vivo." (PMID 23525196, 2013). "The present study demonstrated the protective effects of apelin-13 in MGO-induced UPR and endothelial dysfunction via the AMPK signaling pathway." (PMID 32517197, 2020). "Apelin-13 reduces MGO-induced UPR and endothelial dysfunction via regulating the AMPK activating pathway, suggesting the therapeutic potential of apelin-13 in diabetic cardiovascular complications." (PMID 32517197, 2020). "The ERA patients we investigated presented low baseline levels of apelin along with elevated ADMA levels, which adds support to the hypothesis that endothelial dysfunction in these patients is related to altered NO homeostasis." (PMID 22927708, 2012). "Aortic endothelial dysfunction was addressed by en face immunostaining and acetylcholine-induced vasodilation analysis with aortic rings from mice treated with MGO in the presence or absence of apelin ex vivo." (PMID 32517197, 2020).
diabetic nephropathy (19 papers, 2013 to 2025). "In diabetic nephropathy, apelin signaling suppresses oxidative stress, inflammation, and fibrosis, thereby improving mitochondrial function and restoring antioxidant enzyme expression." (PMID 41515992, 2025). "In diabetic nephropathy (DN) rat models, apelin-13 administration not only decreased blood sugar levels but also improved kidney function and reduced renal fibrosis-related proteins." (PMID 41515992, 2025). "Apelin is a potential therapeutic target for endogenous anti-renal damage and anti-fibrosis in diabetic nephropathy." (PMID 39014438, 2024). "Apelin is a promising endogenous therapeutic target for anti-renal injury and anti-fibrosis in diabetic nephropathy." (PMID 39014438, 2024). "Apelin has also been found to exert reno-protective effects in diabetic nephropathy and ischemia reperfusion by repressing inflammatory response, ROS generation and apoptosis (Day, Cavaglieri & Feliers, 2013) and." (PMID 33850656, 2021). "And apelin, an adipokine which is upregulated in diabetic kidney diseases, was reported to be negatively correlated to TGFβ in polycystic kidney disease and attenuate EMT in renal tubular cells." (PMID 30301930, 2018). "Apelin-mediated angiogenesis and increased permeability in diabetic glomeruli identified a crucial role of apelin in the pathogenesis of diabetic nephropathy." (PMID 23577111, 2013). "Apelin is a novel endogenous peptide recently recognized as a therapeutic target for glucose homeostasis and diabetic complications, and TGF-β is a pleiotropic cytokine associated with progressive diabetic nephropathy and liver injury." (PMID 38178017, 2024). "In contrast, some research has indicated that apelin may aggravate the progression of diabetic nephropathy by inducing podocyte dysfunction and abnormal glomerular angiogenesis." (PMID 31492821, 2019). "In addition apela may participate with apelin in renal protection against fibrosis, ischaemia and diabetic nephropathy." (PMID 28817612, 2017). "Nonetheless, clinical investigations are warranted to explore the therapeutic potential of targeting Apelin and RUNX3 for diabetic nephropathy." (PMID 39014438, 2024). "RUNX3 activated Apelin and regulated the SIRT1/FOXO signaling pathway, resulting in the suppressed cell proliferation and fibrosis in diabetic nephropathy." (PMID 39014438, 2024). "Apelin was demonstrated to exert protective effects in several renal injury models, such as IRI and diabetic kidney disease, by antioxidative, anti-inflammatory, and antiapoptotic effects." (PMID 37723076, 2023). "Finally, our results indicated that tissue regulation of apelin and TGF-β gene expression by hWJ-MSCs-CM also plays a crucial role in improving diabetic nephropathy and hepatopathy." (PMID 38178017, 2024). "As an endogenous physiological regulator with antioxidative, anti-inflammatory and antiapoptotic properties, apelin is becoming a therapeutic target for kidney diseases, including renal ischemia-reperfusion injury (IRI), diabetic nephropathy, and renal fibrosis." (PMID 37723076, 2023). "Consequently, apelin-mediated VEGF secretion and angiogenesis might contribute to glomerular injury in diabetic nephropathy at a certain stage." (PMID 39200188, 2024). "Therefore, it is hypothesized that apelin might inhibit the EMT of podocytes through downregulating the expression and activation of TGFβ/Smad pathway in diabetic kidney diseases." (PMID 30301930, 2018).
liver fibrosis (18 papers, 2017 to 2025). "The apelin signaling pathway has been previously associated with hepatic stellate cell activation and liver fibrosis." (PMID 39594641, 2024). "The peptide apelin is expressed in human healthy livers and is implicated in the development of hepatic fibrosis and cirrhosis." (PMID 33171278, 2021). "The paraplastic hepatocyte is one of the main causes of liver fibrosis; the expression of cyclinD1 was increased in the apelin-13-treated LX-2 cells." (PMID 31270645, 2019). "•Apelin has been implicated in hepatic fibrosis and cirrhosis suggesting that plasma levels of this peptide might be a biomarker of liver disease." (PMID 33171278, 2021). "In addition, the paraplastic hepatocyte was one of the primary causes of liver fibrosis, and the Western blot results showed that the expression level of cyclinD1, one of the cell cycle marker proteins, apparently enhanced the apelin-13 signaling pathway." (PMID 31270645, 2019). "The study showed that apelin was associated with the development of liver fibrosis." (PMID 28484393, 2017). "Indeed, apelin has recently been implicated in the development of hepatic fibrosis and cirrhosis, suggesting that plasma levels of the peptide might be used as a biomarker of disease." (PMID 33171278, 2021). "Furthermore, the in vivo and in vitro assays suggested a key role of apelin in promoting liver fibrosis, and the underlying mechanism might be ascribed to the apelin expression of profibrotic genes via ERK signaling pathway." (PMID 31270645, 2019). "This is in line with other reports demonstrating that apelin plasma levels are reduced in patients with liver fibrosis and cirrhosis." (PMID 40869103, 2025). "This study aimed to investigate the role of miR-125b and its direct and indirect targets of TGF-β, ARs, and apelin in cohorts of well-characterised PSC patients with liver fibrosis." (PMID 40869103, 2025). "It has been reported that the apelin pathway is involved in the progression of pathological and physiological fibrosis, including kidney fibrosis, myocardial fibrosis, hepatic fibrosis, and pulmonary fibrosis." (PMID 36785790, 2023). "Yet, one has to consider that aberrant Apln expression is also found in CD34+ capillarized LSECs in liver fibrosis and cirrhosis and also pro-angiogenic effects were similar to the vascular apelin signaling." (PMID 34658910, 2021). "Plasma apelin was significantly reduced in liver fibrosis (8.3 ± 1.2 pg/ml) and cirrhosis (6.5 ± 0.6 pg/ml) patients compared with controls (15.4 ± 2.0 pg/ml)." (PMID 33171278, 2021). "Plasma from patients with liver fibrosis (n = 14), cirrhosis (n = 56), and healthy controls (n = 25) was solid-phase extracted using a method optimised for recovery of apelin, which was measured by ELISA." (PMID 33171278, 2021). "Apelin is a detrimental mechanism that promotes liver fibrosis mainly via up-regulating the expression of collagen I and platelet-derived growth factor receptor β." (PMID 32207519, 2020). "Here, we briefly review the components of the apelin/APJ system as well as the molecular mechanisms involved in the diverse cellular effects observed so far before focusing on the relationship between the apelin system and the pathogenesis of liver fibrosis." (PMID 31653030, 2019). "Future investigations to further define the mechanisms by which the EC and apelin systems contribute to modulate liver fibrosis will enhance our understanding of their cellular and molecular mechanisms and possible therapeutic targets." (PMID 31653030, 2019). "This review discusses the current understanding of the molecular and cellular mechanisms by which the hepatic endocannabinoid and apelin systems play a significant role in the pathophysiology of liver fibrosis." (PMID 31653030, 2019). "Apelin is a peptide that participates in cardiovascular and renal functions, inflammation, angiogenesis, and hepatic fibrosis through its interaction with the APJ receptor." (PMID 31653030, 2019).